SMO (smoothened, frizzled class receptor)
Diseases named in the same sentence as SMO in open-access papers (continued):
Sharing a sentence is not in itself a finding about the gene and the disease.
medulloblastoma (continued). "This autonomous activation occurs in BCC and medulloblastoma and results from loss-of-function mutations in PTCH or SUFU, or gain-of-function mutations in SMO." (PMID 35163655, 2022). "In medulloblastoma, two SMO inhibitors, sonidegib (LDE225) and vismodegib (GDC-0449), have been used as therapeutics that specifically target this protein." (PMID 34436033, 2021). "PTCH1 LOH has been associated with enhanced medulloblastoma formation as a result of increased SMO and GLI activation, and the loss of GLI1 markedly suppressed spontaneous medulloblastoma formation in Ptc1+/− mice." (PMID 34572373, 2021). "This appears particularly important since loss of primary cilia is a recognized mechanism of resistance to SMO inhibitors in medulloblastoma and BCC57,62." (PMID 33972689, 2021). "Very limited gonadotoxic data are available for patients with medulloblastoma and patients taking SMO inhibitors." (PMID 34298664, 2021). "In mice, activation of SMO resulted in the development of medulloblastoma or basal cell carcinoma, which was blocked by inhibition of cilia formation." (PMID 34674729, 2021). "Like BCCs, most Shh-medulloblastomas are characterized by mutations in the PTCH1 gene, and to a smaller extent, in SUFU and SMO genes." (PMID 34572373, 2021). "A D473H SMO mutant was also found to confer resistance to vismodegib in a medulloblastoma patient and induced GLI1 luciferase reporter activity in C3H10T1/2 cells." (PMID 34572373, 2021). "In the same study, SMO-mediated G-protein activation assay and medulloblastoma cells proliferation confirmed similar potency." (PMID 34831015, 2021). "Monitoring of close to 10,000 phosphopeptides of human medulloblastoma upon short-term stimulation with SMO activators and inhibitors, respectively, allowed us to investigate the complex early phosphosignaling during HH pathway regulation." (PMID 32576205, 2020). "CUR6414 directly binds to SMO to treat basal cell carcinoma, while BMS-833923 directly binds to SMO, reducing the growth of medulloblastoma, pancreatic cancer and cholangiocarcinoma in xenograft mice." (PMID 32962123, 2020). "A phase II trial showed clinical efficacy of the SMO inhibitor vismodegib in adult recurrent SHH medulloblastoma." (PMID 33172502, 2020). "In fact, nearly 90% of sporadic BCC and up to 33% of sporadic medulloblastomas show SHH pathway activation, caused most commonly by inactivating mutations in PTCH1 or more rarely by activating mutations in SMO." (PMID 32957513, 2020). "In particular, germline mutations in Patched1 have been found to be responsible for somatic mutations in medulloblastoma, and 50% of medulloblastomas present loss of PTCH1, loss of SUFU, or gain-of-function of SMO." (PMID 33050158, 2020). "SHH is the predominant group in adult medulloblastomas, and adult SHH tumours are characterised by upstream pathway mutations in PTCH1 and SMO, whereas downstream pathway alterations such as SUFU mutations and MYCN amplifications are rare in this age group." (PMID 33172502, 2020). "TAK-441, an oral SMO inhibitor, suppressed medulloblastoma and pancreatic cancers in mice, as well as mitigated the progression of prostate cancer in mouse xenograft models." (PMID 32962123, 2020). "Several other SMO inhibitors have also been developed in clinical trials for treatment in medulloblastoma." (PMID 30643718, 2019). "Recently, SMO inhibitors have been developed and show utility in the treatment of basal cell carcinoma and the subtype of medulloblastoma dependent on HH signalling." (PMID 30675521, 2019).
medulloblastoma (continued). "This is of particular interest because medulloblastomas resistant to SMO inhibitors have been shown to activate the PI3K/AKT/mTOR pathway." (PMID 31492956, 2019). "The combination of an SMO inhibitor (sonidegib) with a PI3K inhibitor (NVP-BKM120 or NVP-BEZ235) delayed the development of resistance to SMO inhibitor in medulloblastoma animal models." (PMID 30759860, 2019). "Because PTCH1 and SMO work in primary cilia to generate GLI2‐A and GLI3‐A, primary cilia promote the progression of SHH medulloblastoma caused by mutations of PTCH1 and SMO." (PMID 30643718, 2019). "Ligand-independent constitutive activation of GLIs (as a consequence of loss-of-function mutations of PTCH1 or gain-of-function mutations of SMO) drives basal cell carcinoma (BCC) and Shh-type medulloblastoma development." (PMID 31027259, 2019). "Remarkably, pharmacologic mTOR inhibition was found to reduce tumour growth and increase survival in a SMO inhibitor resistant medulloblastoma transgenic mouse model." (PMID 31492956, 2019). "Hh signaling is upregulated in basal cell carcinoma and medulloblastoma and Hh pathway inhibitors targeting the Smoothened (SMO) protein are in clinical use." (PMID 31454140, 2019). "In the Sonic Hedgehog (SHH) subgroup of medulloblastoma (MB), tumor initiation and progression are in part driven by smoothened (SMO) and fibroblast growth factor (FGF)-receptor (FGFR) signaling, respectively." (PMID 31835472, 2019). "A combination of cell-based screening and cheminformatic target prediction identified Smoothib, which was shown to target the heptahelical bundle of SMO, preventing its ciliary localization, and to suppress the growth of Ptch+/− medulloblastoma cells." (PMID 30558232, 2018). "Vismodegib, a SHH pathway inhibitor that binds SMO, was tested in pediatric and adult recurrent medulloblastomas, showing antitumor activity only in the SHH-subgroup of medulloblastomas." (PMID 30279357, 2018). "Meanwhile, even though SMO inhibitor vismodegib (GDC-0449) was reported to have antitumor potency in early clinical studies of medulloblastoma, relapse appeared after treatment." (PMID 30423843, 2018). "A testament to the growth-promoting prowess of GLI proteins in certain cancer types such as basal cell carcinoma and medulloblastoma is the continued reliance of cancerous cells resistant to SMO antagonists on GLI activity." (PMID 29348431, 2018). "Originally, the HH-GLI signaling pathway was targeted at the level of SMO, in an attempt to bypass the inactivating PTCH1 and activating SMO mutations often found in Hedgehog-associated tumors like medulloblastoma and basal cell carcinoma." (PMID 30158435, 2018). "In basal cell carcinoma (BCC) and medulloblastoma, activated Hh signalling is often due to mutations in pathway components such as PTCH and SMO, whereas in other tumour types including breast, mutations are not observed at high frequency." (PMID 28604738, 2017). "In this respect, antagonists of SMO were entered in phase I and II clinical trials, with encouraging results in HH-driven neoplasia, particularly in medulloblastoma and basal cell carcinoma (BCC)." (PMID 28243259, 2017). "SMO inhibitors such as vismodegib, IPI-926 and sonidegib showed high efficacy in cancer types like basal cell carcinoma or medulloblastoma that often harbor activating mutations in the HH pathway." (PMID 28418873, 2017). "Mutations within the drug-binding pocket of the Smoothened (SMO) receptor are reported among basal cell carcinoma (BCC) and medulloblastoma patients who become resistant to the SHH/SMO inhibitor, Vismodegib." (PMID 27608848, 2016).
medulloblastoma (continued). "As a first approach we triggered SMO-independent GLI activation in human medulloblastoma cells (DAOY) by RNAi mediated knockdown of SUFU, a critical negative GLI regulator acting downstream of SMO." (PMID 26784250, 2016). "For example, genetic lesions that enhance PI3K signaling facilitate resistance to imatinib in CML, and activation of MAPK has also been implicated in resistance to SMO inhibitors in BCC patients and a mouse model of SHH medulloblastoma." (PMID 27608848, 2016). "Despite several successful trials with BCC patients and case studies with medulloblastoma (MB) patients, the therapeutic efficacy of SMO targeting is challenged by acquired and de novo drug resistance." (PMID 26784250, 2016). "Although, several smoothened (SMO) antagonists including NVP-LDE225 & GDC0449 are currently being evaluated in clinical trials in patients with medulloblastoma, there is rapid development of tumor resistance." (PMID 26938241, 2016). "Activating mutations in the key components of the SHH pathway PTCH1, SMO and SUFU have been described in medulloblastoma and basal cell carcinoma." (PMID 27825128, 2016). "As assay system we employed HH-responsive, SMO-inhibitor sensitive human medulloblastoma cells (DAOY) and measured changes in the expression of the known HH target genes GLI1 and PTCH as quantitative read-out for pathway activity." (PMID 26784250, 2016). "Patients with Hh-activated medulloblastoma have also responded to treatment with vismodegib and the SMO inhibitor sonidegib." (PMID 24598114, 2014). "Given this, we screened human cell lines for their SMO expression level and identified high level SMO expression in the Daoy human medulloblastoma (MB) cell line." (PMID 23762360, 2013). "Clinical examples include basal cell carcinoma (BCC), medulloblastoma, and other human tumors that are usually associated with mutations of Hh signaling components including PTC1 and SMO." (PMID 24302888, 2013). "Those tumors sensitive to SMO inhibitors including basal cell carcinoma and medulloblastoma rely on canonical HH signaling for survival." (PMID 23097684, 2012). "Those tumors sensitive to SMO inhibitors, which include basal cell carcinoma and medulloblastoma, rely on canonical HH signaling for cellular survival." (PMID 21860067, 2011). "Spontaneous mutations in PTCH and SMO that confer aberrant pathway activity are also commonly found in spontaneous cases of BCC and medulloblastoma." (PMID 21203400, 2010). "These metabolite profiles closely mirror those reported from human medulloblastomas confirming that SMO mice provide a realistic model for investigating metabolic aspects of this disease." (PMID 20842126, 2010). "The SMO mouse model has high levels of the activated form of SMO receptor in Sonic hedgehog (Shh) signalling pathway, which results in a high rate of medulloblastoma formation and early cerebellar hyperproliferation." (PMID 20842126, 2010). "The mutations in the patched (Ptch) gene in the Shh pathway contribute to SMO mice developing subclinical medulloblastoma by two months of age." (PMID 20842126, 2010). "Thus, p38α-mediated phosphorylation on Ser937 of GLI1 was involved in the tumorigenesis of medulloblastoma and the sensitivity to chemotherapy of SMO antagonists." (PMID 38307877, 2024). "Another SMO inhibitor, steroidal alkaloid cyclopamine, is a natural plant product that directly antagonizes Hh in vivo and is currently under phase II clinical trials for medulloblastoma [ NCT01878617]." (PMID 37305676, 2023). "Additionally, the agents ALLO1 and ALLO2 have been found to inhibit SMO through a different mechanism involving the cysteine-rich domain and have shown anti-proliferative effects in medulloblastoma cells." (PMID 37568705, 2023). "Furthermore, PTCH1, DDX3X and SMO driver mutations characteristic to SHH medulloblastomas, and PRDM6 enhancer hijacking driver events found in Group 4-medulloblastomas associated with MuAt features (FDR<1%)." (PMID 37420249, 2023).
medulloblastoma (continued). "Notably, JQ1, a BRD4 inhibitor, was shown to inhibit the SHH-mediated proliferation of several tumors, including medulloblastomas, and to overcome their resistance to SMO antagonists." (PMID 37568705, 2023). "Mutations in PTCH1 and SMO, although to a lesser degree than BCC, have also been detected in other cancers such as medulloblastoma, mesothelioma, cervical cancer, breast cancer, odontogenic keratocystic tumors, acute lymphoblastic leukemia, and hepatocellular carcinoma (HCC)." (PMID 34572373, 2021). "In addition, the PI3K pathway functions in therapeutic resistance against SMO inhibitors in medulloblastoma and esophageal adenocarcinoma." (PMID 34268113, 2021). "Combinatory inhibition of both PI3K and HH signaling pathways in preclinical studies on medulloblastoma have demonstrated favorable efficacy in attenuating SMO inhibitor-resistant tumors, although the effects on other HH-mediated cancers like BCC remains to be determined." (PMID 34268113, 2021). "The overall ambition is to identify novel, more precise predictive and minimal residual disease biomarkers for response prediction to radiotherapy, conventional chemotherapy, and SMO inhibition in post-pubertal SHH medulloblastoma patients to inform the next generation of trials." (PMID 34298664, 2021). "In addition, SMO inhibitor-resistant mouse medulloblastoma are still sensitive to PI3K inhibition and combination therapy with the GLI inhibitor GANT61 and PI3K/MTOR inhibitor PI103 synergistically inhibited tumors in a HH-driven rhabdomyosarcoma mouse model." (PMID 34268113, 2021). "Most prior drug development has focused on developing inhibitors of the G protein-coupled receptor (GPCR) and HH signal transducer SMO, and SMO inhibitors are used in the clinic for the treatment of patients with basal cell carcinoma, medulloblastoma, and acute myeloid leukemia." (PMID 34890564, 2021). "In addition, interesting synergistic effects on SMO function have been reported between statins, used to suppress cholesterol biosynthesis, and the SMO antagonist vismodegib, in the treatment of medulloblastoma." (PMID 30595453, 2019). "So-called SMO-inhibitors, such as cyclopamine or vismodegib, are currently being used as monotherapy due to promising preclinical results in clinical trials to prevent medulloblastoma and basal cell carcinoma." (PMID 30769952, 2019). "GRK2 can regulate SHH/SMO signaling at different points along their signaling pathway and is expressed in medulloblastomas, but to date, has not been implicated in medulloblastoma biology." (PMID 31554835, 2019). "Patients with SHH-driven medulloblastoma frequently exhibit either germline or somatic mutations and copy-number alterations in genes that regulate the Hedgehog (HH) signalling pathway such as PTCH1, SUFU, SMO, GLI1, GLI2 and MYCN8." (PMID 31492956, 2019). "Third, it was previously reported that the stimulatory G protein Gs acts as a tumour suppressor in basal cell carcinoma and medulloblastoma, which are caused by mutations in PTCH1 or SMO that results in constitutive SMO activation and high GLI transcriptional activity." (PMID 30148884, 2018). "Also, itraconazole, a commonly used antifungal agent that works via inhibiting Hh signaling, was reported to inhibit the growth of medulloblastoma in a mouse allograft model, specifically through the inhibition of SMO." (PMID 30423843, 2018). "The study of the molecular features of medulloblastoma subgroups is also of some help for the analysis of the differential response of medulloblastoma patients to new drugs entered into the experimental therapy of these tumors, such as SMO (smoothened) inhibitors." (PMID 30279357, 2018). "Interestingly, upregulation of the PI3K pathway was found as a resistance mechanism against a SMO antagonist in medulloblastoma, indicating a clinically relevant interaction of both pathways." (PMID 28418873, 2017).
medulloblastoma (continued). "The identical recurrent mutation in SMO that accounts for the multiple malformations in CJS is also observed in several cancers including ameloblastoma, basal cell carcinoma, medulloblastoma, and meningioma." (PMID 28386950, 2017). "Arsenic trioxide, which targets GLI2 for degradation, inhibits the growth of Vismodegib-resistant medulloblastoma in vivo, and the combination of arsenic trioxide and itraconazole, a SMO inhibitor, shows greater anti-tumor efficacy in vivo than either agent alone." (PMID 27608848, 2016). "Also, Vismodegib- or NVP-LDE225- (SMO/SHH pathway inhibitors) resistant BCCs patients and mouse medulloblastoma cells have been shown to acquire mutations in SUFU or amplification of a downstream transcriptional effector of the SHH signaling pathway, GLI2." (PMID 27608848, 2016). "However, the response to SMO inhibitors of medulloblastoma patients was variable and transient, and this drug was most effective in treating tumors with upstream activating aberrations in the SHH pathway." (PMID 27519263, 2016). "Inhibitors targeting SMO for curing medulloblastoma tumors are in clinical trials." (PMID 23251412, 2012). "In the light of the present knowledge, the SMO and adult medulloblastomas share metabolite similarities such as high CCM and taurine, and low NAA, but levels of creatine and lactate/lipids in these tumours may be at variance." (PMID 20842126, 2010). "Distinct tumors, such as BCC and medulloblastoma, may harbor mutations in PTCH1 or SMO that leads to constitutive pathway activation in the absence of HH ligand." (PMID 21203400, 2010). "Interestingly, we found that the metabolites pattern of the SMO medulloblastoma resembles that of human medulloblastomas which have already metastasised." (PMID 20842126, 2010). "The HH pathway may be activated through a cell autonomous mechanism, as seen in medulloblastomas in which mutant SMO is constitutively active." (PMID 19834598, 2009). "The initial medulloblastoma mouse models followed the discovery of frequent mutations of the patched (PTCH) gene (i.e. the sonic hedgehog (SHH) receptor) and downstream signalling factors (SUFU, SMO and GLI) in medulloblastoma derived from the external granular layer." (PMID 39324445, 2024). "Adult SHH-activated medulloblastomas display a higher mutation burden compared to their pediatric counterparts, particularly with mutations associated with the SHH pathway, mainly Patched1 (PTCH1) and Smoothened (SMO), as well as mutations in CREB binding protein (CREBBP), BRPF1, and TERT promoter." (PMID 37568705, 2023). "Thus, CK1α activators could address a significant unmet clinical need for patients with medulloblastoma resistant to SMO inhibitors." (PMID 35163655, 2022). "Consequently, pharmacological inhibition of PI3K/AKT signaling may also represent a promising therapeutic approach to treat SMO inhibitor-resistant medulloblastoma." (PMID 35163655, 2022). "In addition to these GLI antagonists, casein kinase 1α (CK1α) may be a powerful and innovative approach in treating patients with medulloblastoma resistant to SMO inhibitors." (PMID 35163655, 2022). "Therefore, targeting HDAC may be therapeutically useful for patients with Shh-dependent medulloblastoma, including the cancer type resistant to SMO inhibitors." (PMID 35163655, 2022). "Characterized by developmental abnormalities and distinct postnatal cancer occurrence including medulloblastoma (1–2% of cases) and rhabdomyosarcoma (0.5% of cases), Gorlin syndrome primarily results from inactivating PTCH1 mutations on chromosome 9, leading to SMO hyperactivity." (PMID 32957513, 2020). "SHH medulloblastomas show unregulated ligand-independent SHH pathway signaling due to mutations/alterations such as loss-of-function of PATCHED (PTCH1) or Suppressor of Fused (SUFU), gain-of-function of Smoothened (SMO), GLI1, GLI2, or MYCN, and/or other alterations." (PMID 31554835, 2019).